WRN (WRN RecQ like helicase)
Diseases named in the same sentence as WRN in open-access papers (continued):
Sharing a sentence is not in itself a finding about the gene and the disease.
WRN also shares sentences with these, for which no sentence is quoted: Hutchinson-Gilford progeria syndrome (7 papers); ataxia telangiectasia (3); autosomal recessive disease (3); Insulin resistance (3); lung carcinoma (3); Age-related cataract (2); Alzheimer disease (2); dyslipidemia (2); myocardial infarction (2); protein deficiency (2); skin cancer (2); acquired lipodystrophy (1); adult T-cell leukemia (1); age (1); aging (1); Alpha-thalassemia (1); B-cell lymphoma (1); Berardinelli-Seip congenital lipodystrophy (1); bone sarcoma (1); bone tumors (1); brain disorder (1); CANDLE syndrome (1); central nervous system diseases (1); cervical incompetence (1); chordoma (1); coronary artery disease (1); cystoid macular edema (1); Diamond-Blackfan anemia (1); dyskeratosis congenita (1); familial colorectal cancer (1).
A further 33 diseases each share a sentence with WRN in 1 paper.